APBA2 (amyloid beta precursor protein binding family A member 2)
Description:
May modulate processing of the amyloid-beta precursor protein (APP) and hence formation of APP-beta.
Synonyms: MINT2; X11L; D15S1518E; LIN-10; MGC:14091; HsT16821; X11-BETA
Tractability: Antibody: its Gene Ontology location is reachable by antibodies, with medium confidence. PROTAC: ubiquitination databases record sites on it; its protein half-life has been measured.
Gene: Protein-coding gene on chromosome 15 (28,884,449 to 29,118,317, forward strand). Ensembl gene ENSG00000034053.
Subcellular location (Human Protein Atlas): Golgi apparatus
Pathways (Reactome):
Neuronal System: Neurexins and neuroligins
Gene Ontology:
Molecular function: identical protein binding; protein binding; amyloid-beta binding
Biological process: chemical synaptic transmission; nervous system development; presynaptic modulation of chemical synaptic transmission
Cellular component: Golgi apparatus; cytoplasm; dendritic spine; plasma membrane; presynapse; Schaffer collateral - CA1 synapse
Genetic constraint (gnomAD): Loss-of-function variants: 30 observed, 77.7 expected, observed/expected ratio (o/e) 0.39, 90% interval 0.29 to 0.52. The upper end of that interval is the gene's LOEUF score, 0.52, which puts it in group 2 of 6, group 1 being the genes least tolerant of losing a copy. Missense variants: 801 observed, 1,060.5 expected, observed/expected ratio (o/e) 0.76, 90% interval 0.71 to 0.8. Synonymous variants: 444 observed, 427.54 expected, observed/expected ratio (o/e) 1.04, 90% interval 0.96 to 1.12.
Homologues: Orthologues: macaque APBA2 (98% identical), chimpanzee APBA2 (98% identical), mouse Apba2 (93% identical), rat Apba2 (92% identical), guinea pig APBA2 (92% identical), dog APBA2 (91% identical), pig APBA2 (91% identical), rabbit APBA2 (84% identical), tropical clawed frog apba2 (78% identical), zebrafish apba2b (75% identical), zebrafish apba2a (50% identical), Drosophila melanogaster X11Lbeta (42% identical), and 1 more. Paralogues in human: APBA1 (55% identical), APBA3 (35% identical), SDCBP (11% identical), SDCBP2 (8% identical).
Diseases named in the same sentence as APBA2 in open-access papers:
APBA2 is named in the same sentence as 38 diseases in open-access papers, as found by Europe PMC text mining. Sharing a sentence is not in itself a finding about the gene and the disease. The quoted sentences say what the papers report.
Alzheimer disease (6 papers, 2013 to 2025). A progressive, neurodegenerative disease characterized by loss of function and death of nerve cells in several areas of the brain leading to loss of cognitive function such as memory and language. "APBA2 stabilizes amyloid precursor protein, which plays a key role in the development of Alzheimer’s disease." (PMID 35390271, 2022). "The only candidate that was found to be differentially expressed in our results and in validation data is APBA2; this protein interacts with amyloid precursor proteins which are involved in the development of Alzheimer’s disease." (PMID 33680922, 2020). "Remarkably, some of them are targeted by more than one miRNA, such as APBA2, which are involved in the “Alzheimer disease–amyloid secretase pathway” together with the CHRNA7 and MAPK10 genes, corroborating the importance of the regulation of their gene expression in AD." (PMID 40243843, 2025). "It is interestingly to note that three (APBA2, APBA3 and NINJ2) of these genes are correlated with Alzheimer’s disease." (PMID 24367640, 2013). "APBA2, the amyloid ß precursor protein binding A2 (aka X11ß, MINT2), is principally recognized for its role in synaptic vesicle exocytosis and its ability to stabilize amyloid precursor protein (APP), and is considered part of the genetic signature of Alzheimer's disease in Down syndrome." (PMID 37303712, 2023).
autism (6 papers, 2011 to 2022). Persistent deficits in social interaction and communication and interaction as well as a markedly restricted repertoire of activity and interest as well as repetitive patterns of behavior. "Analyses of genomic deletions have implicated APBA2 (also known as MINT2 and X11L) in autism and schizophrenia pathogenesis." (PMID 32171335, 2020). "Large AS deletions that include APBA2 in 15q13.1 have been reported and a small duplication of 15q13.1 has been described in a family with a history of autism." (PMID 21824424, 2011).
gastric cancer (3 papers, 2009 to 2020). A primary or metastatic malignant neoplasm involving the stomach. "APBA2 encodes a tumor suppressor and was found to be hypermethylated in various cancers, and SLC43A2 was reported to be associated with gastric cancer; however, the prognostic value of these two genes is unclear." (PMID 33221755, 2020). "Another tumor suppressor is APBA2 (amyloid beta (A4) precursor protein-binding, family A, member 2; also known as MINT2), which is frequently methylated and silent in colorectal carcinoma and gastric carcinoma." (PMID 20015385, 2009).
schizophrenia (3 papers, 2009 to 2020). A major psychotic disorder characterized by abnormalities in the perception or expression of reality. "The decreased expression of APBA2 has been identified in superior temporal gyrus in schizophrenia patients and gender-specific alterations in the expression of APBA2 have been found in dopamine neurons." (PMID 33680922, 2020). "More encouragingly, however, despite the rarity of these events, we nonetheless replicated several specific regions from previous studies that were not known to be recurrent schizophrenia-associated CNVs, including those affecting APBA2 and the surrounding region." (PMID 19197363, 2009).
endometrial carcinoma (2 papers, 2006 to 2010). A malignant tumor arising from the epithelium that lines the cavity of the uterine body. "Also at 12 h of gefitinib treatment, APBA2 and RSP2, previously found to be highly expressed in endometrial carcinomas and prostate cancer, respectively, were inhibited." (PMID 20579378, 2010).
ovarian carcinoma (2 papers, 2006 to 2017). A malignant neoplasm originating from the surface ovarian epithelium. "Eight loci (PABPC4L, APBA2, FAM189A1, FUT7, ENTPD2, NPDC1, C9orf139 and L1CAM) were associated with risks for both breast cancer and ovarian cancer (P<0.05)." (PMID 28145423, 2017).
age-related macular degeneration (1 paper, 2021). Age-related loss of vision in the central portion of the retina (macula), secondary to retinal degeneration. "In a study that reported the activity of APBA2, it was reported in patients with age-related macular degeneration (AMD), and autophagy factors were identified by treating ARPE-19 cells with soluble amyloid with an oligomer." (PMID 34016123, 2021).
albinism (1 paper, 2013). A congenital disorder characterized by partial or complete absence of melanin pigment in the eyes, hair, or skin. "However, GRM5 and APBA2 lie 396 kb upstream and 1025 kb upstream of TYR and OCA2, respectively, two well-known pigmentary genes for which a complete loss-of-function causes albinism in humans and in other animals." (PMID 23555287, 2013).
Blindness (1 paper, 2013). Blindness is the condition of lacking visual perception defined as a profound reduction in visual perception. "In particular, loss-of-function for OCA2 can cause blindness due to loss of melanin from retinal pigment epithelial cells, and we speculate that natural selection for the APBA2 region in Europeans represents cell type-specific regulation that promotes fair skin while preserving visual function." (PMID 23555287, 2013).
Borderline personality disorder (1 paper, 2013). A personality disorder characterized by impulsive behavior and unpredictable, capricious mood. "Thus it is tempting to speculate that epigenetic alteration of APBA2 and APBA3 may contribute to borderline personality disorder." (PMID 24367640, 2013).
depression (1 paper, 2015). "In human brain of depression patients, we then identified the potential genes, amyloid beta (A4) precursor protein-binding, family A, member 2 (APBA2), well known AD modulators by integrating datasets from neuropathology, microarray, and RNA seq." (PMID 26449188, 2015). "5-HT6R mRNA was significantly correlated with APBA1 and APBA2 in brain tissues of depression patients." (PMID 26449188, 2015). "We further explored correlation between expression levels of two ABPA genes such as APBA1 and APBA2 and those of serotonin receptors in the hippocampus of individuals with depression and unaffected controls using RNA sequencing data which were deposited in the SNCID." (PMID 26449188, 2015).
Huntington disease (1 paper, 2022). Huntington disease (HD) is a rare neurodegenerative disorder of the central nervous system characterized by unwanted choreatic movements, behavioral and psychiatric disturbances and dementia. "Other genes highlighted by this study include CD320, which was reported to be associated with Huntington’s disease in a previous EWAS; USP43, which was shown to have DNAm levels associated with progressive supranuclear palsy; APBA2, which was reported in an EWAS of Parkinson’s disease (PD)." (PMID 36359320, 2022).
Intellectual disability (1 paper, 2017). "Genes APBA2, NDNL2 and TJP1 that are triplicated in case VI may be responsible for the more severe intellectual disability." (PMID 28174603, 2017).
Leukoencephalopathy (1 paper, 2010). This term describes abnormality of the white matter of the cerebrum resulting from damage to the myelin sheaths of nerve cells. "Downregulated genes included amyloid beta precursor protein‐binding, family a member 2 (APBA2); glycoprotein m6a (GPM6A); megalencephalic leukoencephalopathy with subcortical cysts 1 (MLC1); ankyrin repeat and btb domain containing 2 (ABTB2); and ring finger protein 43 (RNF43)." (PMID 19793339, 2010).
lung disease (1 paper, 2025). "The remaining 11 genes in the region encode proteins associated with neurologic disorders (APBA2, CHRFAM7A, MTMR10, FAN1), skin and eye pigmentation or development (OCA2, HERC2, TJP1, TRPM1), nephritis (ARHGAP11B, MTMR10, FAN1), and lung disease (ENTREP2, NSMCE3)." (PMID 40013929, 2025).
tumor (6 papers, 2009 to 2023). "ERBB2 and CCR1 were genes activated in late EECs, while APBA2 (MINT2) and CDK inhibitor p16 tumor suppressors in early EECs." (PMID 20015385, 2009).
cancer (4 papers, 2006 to 2020). A tumor composed of atypical neoplastic, often pleomorphic cells that invade other tissues. "Aberrant methylation of APBA2/MINT2 and APBA3/MINT3 were not previously reported in psychiatric disease however frequently observed in cancer." (PMID 24367640, 2013).
neurodegenerative disease (1 paper, 2022). A disorder of the central nervous system characterized by gradual and progressive loss of neural tissue and neurologic function. "These include SNCA, SEPW1, ITPK1, and APBA2, which have all been previously implicated to relate to neurodegenerative diseases and/or cognitive functioning." (PMID 36359320, 2022).
APBA2 also shares sentences with these, for which no sentence is quoted: adenoma (2 papers); colorectal cancer (2); epilepsy (2); Angelman syndrome (1); autism spectrum disorder (1); breast carcinoma (1); cervical cancer (1); colon cancer (1); colorectal tumours (1); Down syndrome (1); gastric MALT lymphoma (1); infection (1); metastasis (1); metastatic tumor (1); nephritis (1); neurologic disorders (1); progressive supranuclear palsy (1); prostate carcinoma (1); psychiatric disease (1); rectal carcinoid tumors (1).